EEF2 (eukaryotic translation elongation factor 2)
Diseases named in the same sentence as EEF2 in open-access papers (continued):
Sharing a sentence is not in itself a finding about the gene and the disease.
ovarian carcinoma (2 papers, 2020 to 2023). A malignant neoplasm originating from the surface ovarian epithelium. "Specifically, LIG1 is an attractive target for personalization of ovarian cancer therapy, and decreased eEF2 phosphorylation, mediated by increased PP2A activity, contributes to resistance to HER2 inhibition." (PMID 37519889, 2023).
renal cell carcinoma (2 papers, 2022 to 2023). "From OMIM genes, the top-ranked gene-cancer association was EEF2 (Log2OR = 5.38, FDR = 1.40 × 10−3) with renal cell carcinoma (Kidney-RCC)." (PMID 38143269, 2023).
triple-negative breast carcinoma (2 papers, 2020 to 2026). An invasive breast carcinoma which is negative for expression of estrogen receptor (ER), progesterone receptor (PR), and human epidermal growth factor receptor 2 (HER2). "Increasing evidence has demonstrated that FoxM1 accelerates tumor invasion and migration by regulating eukaryotic extension factor 2 kinase eEF2 in triple negative breast cancer." (PMID 32035486, 2020).
type 1 diabetes (2 papers, 2021 to 2022). "The main effect of the group showed that eEF2 phosphorylation (i.e. inactivation) was higher in type 1 diabetes than control." (PMID 34995365, 2022). "Aerobic exercise combined with resistance exercise is able to enhance the activation of EEF2, contributing to improved glycemic control and maintenance of muscle health in type 1 diabetes." (PMID 34421625, 2021).
acute respiratory distress syndrome (1 paper, 2020). Progressive and life-threatening pulmonary distress in the absence of an underlying pulmonary condition, usually following major trauma or surgery. "Thus, miR‐642a‐5p and eEF2 may serve as potential targets for acute lung injury/acute respiratory distress syndrome diagnosis or treatment." (PMID 32881411, 2020).
anaplastic large cell lymphoma (1 paper, 2018). Anaplastic large cell lymphoma (ALCL) is a rare and aggressive peripheral T-cell non-Hodgkin lymphoma, belonging to the group of CD30-positive lymphoproliferative disorders, which affects lymph nodes and extranodal sites. "Similarly, reduced transcript levels of EEF2 were observed in follicular lymphoma and T-Cell/histiocyte-rich large B-Cell lymphoma, in Eckerle’s dataset, as opposed to overexpression in anaplastic large cell lymphoma in the same dataset." (PMID 29342219, 2018).
aneurysm (1 paper, 2025). Bulging or ballooning in an area of an artery secondary to arterial wall weakening. "While captopril offers hemodynamic benefits that slow aneurysm expansion by lowering blood pressure, the ability of cabamiquine to inhibit VSMC phenotypic switching via suppressing eEF2 activity offers a more direct approach for disrupting the cellular pathways underlying AAD progression." (PMID 40698138, 2025).
cholangiocarcinoma (1 paper, 2026). A carcinoma that arises from the intrahepatic biliary tree (intrahepatic cholangiocarcinoma) or from the junction, or adjacent to the junction, of the right and left hepatic ducts (hilar cholangiocarcinoma). "RFC4, HDGF, and TPM4 showed higher gain mutation frequencies, while eukaryotic translation elongation factor 2 (EEF2) and ENO1 had higher loss mutation frequencies across ovarian serous cystadenocarcinoma, uterine carcinosarcoma, and cholangiocarcinoma." (PMID 41328179, 2026).
chronic lymphocytic leukemia (1 paper, 2024). "In chronic lymphocytic leukemia (CLL), targeting the eEF2/eEF2K axis through phosphorylation effectively suppresses disease progression by modulating proteins critical for cell proliferation." (PMID 39707196, 2024). "In chronic lymphocytic leukemia (CLL), inhibiting mammalian target of rapamycin complex 1 (mTORC1) reduces eEF2 activity, leading to decreased synthesis of cell cycle proteins and halting CLL progression." (PMID 39707196, 2024).
colon adenocarcinoma (1 paper, 2021). "Similar results are seen for the protein expression of RPL24, eEF2K, and eEF2 from colon adenocarcinoma samples, and for the three mRNAs in rectal adenocarcinoma." (PMID 34895463, 2021). "(B) RNA expression levels of RPL24, EEF2K, and EEF2 between normal colon and colon adenocarcinoma samples using data extracted from The Cancer Genome Atlas by TNMplot." (PMID 34895463, 2021).
diabetes (1 paper, 2022). "Hence, in light of the involvement of ghrelin signalling and eEF2 in obesity, diabetes and carcinogenesis, the control of eEF2 phosphorylation upon activation of GHS-R1α emerges as an attractive therapeutic strategy." (PMID 35841486, 2022).
endometriosis (1 paper, 2023). The growth of functional endometrial tissue in anatomic sites outside the uterine body. "One of the genes annotated to these differentially methylated sites, EEF2 (eukaryotic translation elongation factor 2), is downregulated in ectopic endometriosis lesions." (PMID 37587191, 2023).
fragile X syndrome (1 paper, 2015). A genetic syndrome caused by mutations in the FMR1 gene which is responsible for the expression of the fragile X mental retardation 1 protein. "Park found that most protein synthesis was inhibited in a mouse model of fragile X syndrome when eEF-2 was phosphorylated, while the expression of Arc/Arg 3.1 increased significantly." (PMID 25962137, 2015).
fungal infections (1 paper, 2019). "Depurination of a specific nucleotide in the SRL RNA by RIPs is a mechanism in plants to limit the spread of fungal infections: it impairs binding of the eEF2/GTP complex to the ribosome." (PMID 30856238, 2019).
HCMV infection (1 paper, 2021). "In our proposed model, PP1 inhibition by 1E7-03 leads to early AMPK activation and EEF2 inactivation, followed by attenuated translation and inhibition of lytic HCMV infection." (PMID 34335531, 2021). "Similar to PP1 inhibition using 1E7-03, also siRNA-mediated knockdown of PP1 led to phosphorylation of AMPK and EEF2 during CMV infection." (PMID 34335531, 2021).
hearing loss (1 paper, 2022). "Three autophagy-related genes (Dram1, Fkbp1b, and Fos) were differentially expressed in the mild hearing loss group, whereas five autophagy-related genes (Dram1, Fkbp1b, Fos, Capn2, and Eef2) were differentially expressed in the severe hearing loss group." (PMID 35463035, 2022).
intellectual disability syndrome (1 paper, 2020). "Why the loss of eEF2-diphthamide modification leads to an intellectual disability syndrome is unclear." (PMID 32576952, 2020).
invasive breast carcinoma (1 paper, 2018). A carcinoma that infiltrates the breast parenchyma. "In a single analysis of Finak’s dataset, both EEF1D and EEF2 mRNA levels were significantly reduced in invasive breast carcinoma, compared to normal tissue." (PMID 29342219, 2018).
Kidney clear cell carcinoma (1 paper, 2018). "As per TCGA analysis, expression levels of EEF1A1, EEF1B2, EEF1G, EEF1D and EEF2 were significantly upregulated in kidney clear cell carcinoma while that of EEF1E1 was downregulated." (PMID 29342219, 2018). "SurvExpress analysis using TCGA-KIRC (Kidney clear cell carcinoma) dataset showed that higher expression levels of EEF1A1, EEF1G and EEF2 predicted better survival in low-risk group patients." (PMID 29342219, 2018).
lung squamous cell carcinoma (1 paper, 2017). "Importantly, EEF2 is elevated in lung squamous cell carcinoma and elevated levels of EEF2 drive cell proliferation and promote EMT." (PMID 29282095, 2017).
male infertility (1 paper, 2025). The inability of the male to effect fertilization of an ovum after a specified period of unprotected intercourse. "Eukaryotic elongation factor 2 (EEF2) is another potential target gene that might be crucial for protein synthesis during spermatogenesis because studies indicated that disruptions in EEF2 function can lead to male infertility, as seen in transgenic mice models with premature mRNA translation." (PMID 40141332, 2025).
medulloblastoma (1 paper, 2018). A malignant, invasive embryonal neoplasm arising from the cerebellum. "Similarly for EEF2, Pomeroy’s datasets exhibited increased transcript levels in desmoplastic medulloblastoma, classic medulloblastoma and rhabdoid tumor." (PMID 29342219, 2018).
memory impairment (1 paper, 2022). "In summary, Scn1a ± mice exhibited increased levels of eEF2 phosphorylation that were associated with EEG alterations and a greater responsiveness to seizures accompanied by behavioral abnormalities including memory impairment, ASD like behavior and motor coordination problems." (PMID 34980259, 2022).
polyposis (1 paper, 2023). "Prior studies reported that rapamycin prevents APC-deficiency induced polyposis in several mouse models by inhibiting translation-related targets such as mTORC1, S6 and eEF2." (PMID 37138032, 2023).
renal fibrosis (1 paper, 2025). A final common manifestation of a wide variety of chronic kidney diseases characterized by glomerulosclerosis and tubulointerstitial fibrosis. "In particular, we performed chemical proteomic analyses and found that Elongation factor 2 (EEF2) is the key target of compound 1 for anti-renal fibrosis in vitro." (PMID 40654341, 2025).
spinocerebellar ataxia type 26 (1 paper, 2017). Spinocerebellar ataxia type 26 (SCA26) is a very rare subtype of autosomal dominant cerebellar ataxia type III (ADCA type III) characterized by late-onset and slowly progressive cerebellar signs (gait ataxia) and eye movement abnormalities. "Mutations in Eef2 and Itpr1 cause spinocerebellar ataxia type 26 and 15/29, respectively." (PMID 28893375, 2017).
Stroke (1 paper, 2023). Sudden impairment of blood flow to a part of the brain due to occlusion or rupture of an artery to the brain. "Our research findings highlight the significance of genes associated with the UPR pathway, including ATF6, EXOSC5, EEF2, LSM4, NOLC1, BANF1, and DNAJC3, in the occurrence of stroke." (PMID 37891634, 2023).
systemic lupus erythematosus (1 paper, 2013). An autoimmune multi-organ disease typically associated with vasculopathy and autoantibody production. "Also, circulating aAbs directed against eEF2 kinase were reported in patients with systemic lupus erythematosus and such response involving eEF2 kinase and possibly eEF2 itself could therefore represent a more general response against stress-related and/or starvation-related conditions." (PMID 24130777, 2013).
T-cell lymphomas (1 paper, 2021). "For example, diphtheria toxin, which ADP-ribosylates eEF2, conjugated to interleukin-2 (ONTAK) has been approved by the FDA for the treatment of T-cell lymphomas." (PMID 34508355, 2021).
vitiligo (1 paper, 2024). Generalized well circumscribed patches of leukoderma that are generally distributed over symmetric body locations and is due to autoimmune destruction of melanocytes. "The role of EEF2, EEF1G and PSMA2 in vitiligo or inflammation pathways remains unclear." (PMID 38715599, 2024).
cancer (64 papers, 2010 to 2025). A tumor composed of atypical neoplastic, often pleomorphic cells that invade other tissues. "Although studies have linked aberrant eEF2 expression to various cancers, research has primarily focused on its structure, highlighting a need for deeper exploration into its molecular functions." (PMID 39707196, 2024). "Different modifications and the associated molecular signaling pathways of eEF2 have been found to be aberrant in various types of cancers." (PMID 39707196, 2024). "Despite the significance of eEF2 in cancer, its precise functions and underlying mechanisms remain elusive, highlighting the need for further investigation." (PMID 39707196, 2024). "EEF2 was also identified as a tumor associated antigen overexpressed in the majority of several types of cancers and plays an oncogenic role in cancer cell growth." (PMID 29342219, 2018). "Overall, we see that in addition to EEF1A2; EEF1G, EEF1D, EEF1E1 and EEF2 are significantly upregulated in different cancer types and are associated with better and worse survival outcome in specific cancers." (PMID 29342219, 2018). "Thus, eEF2 emerges as a crucial mediator in the complex signaling pathways underlying cancer progression and treatment resistance." (PMID 39707196, 2024). "Additionally, the eukaryotic elongation factor 2 kinase (eEF2K), responsible for inhibitory eEF2 phosphorylation that impedes protein synthesis, is overexpressed in several cancers and associated with poor survival outcomes." (PMID 37747887, 2023). "Based on these findings showing the involvement of eEF2 in cancer cell growth, it is unlikely that antigenic loss of eEF2 could become a mechanism of tumor escape from eEF2-specific immune responses." (PMID 24589652, 2014). "Thus, variations or mutations that interfere with the functionality of the DPH1 may be biomarkers that associate with the response of cancer cells to targeted toxins that ADP-ribosylate the diphthamide on eEF2." (PMID 28245596, 2017). "Pseudomonas aeruginosa releases a potent virulence factor capable of destroying cancer cells via ADP-ribosylation of the eukaryotic elongation factor 2 (eEF2)." (PMID 40075568, 2025). "Studies have shown that eEF2 protein levels are significantly elevated in many different cancer types compared to normal tissues." (PMID 40240912, 2025). "Although numerous compounds have been discovered to inhibit eEF2-related molecular signaling and enhance its phosphorylation level in different cancer cells, there is a scarcity of reported inhibitors that directly target eEF2 or its associated complexes." (PMID 39707196, 2024). "eEF2 is pivotal in cancer transformation and progression, influencing protein synthesis dynamics across various tumor types." (PMID 39707196, 2024). "Although extensive research has been conducted on the structure of eEF2, its functions in cancer have received less attention." (PMID 39707196, 2024). "Further, utilizing the data in the CPTAC-TCGA datasets containing 364 TCGA cancer samples, we also detected eEF2K and eEF2 protein phosphorylation site in different cancer types and analyzed the changes of eEF2K and eEF2 protein phosphorylation levels." (PMID 39592671, 2024). "This modification enhances eEF2’s interaction with the ribosome, promoting protein synthesis and cancer cell proliferation." (PMID 39707196, 2024). "Enhancing eEF2-mediated translation resolves this conflict, promoting the synthesis of pro-proliferative mRNAs and driving cancer progression, thereby highlighting eEF2 as a potential therapeutic target." (PMID 39707196, 2024). "In inhibitor research, the text underscores the significance of understanding the intricate mechanisms of eEF2 in protein translation and their implications in cancer progression." (PMID 39707196, 2024).
cancer (continued). "In the qPhos protein dynamic modification database, eEF2 has been identified as being subjected to diverse modifications in different cancer cells, including phosphorylation, diphthamide modification, SUMOylation, and ubiquitylation, among others." (PMID 39707196, 2024). "Nonetheless, another study discovered that NH125 inhibited the proliferation ability of various cancer cells and evoked the accumulation of phosphorylated eEF2." (PMID 39707196, 2024). "Collectively, these findings underscore the central role of eEF2 phosphorylation in inhibiting protein synthesis and tumor growth across multiple cancer types, making it a promising target for therapeutic intervention." (PMID 39707196, 2024). "As advancements continue in this field, the development of novel eEF2 inhibitors holds great promise for enhancing the efficacy of cancer treatments by disrupting critical pathways that support cancer cell growth and survival." (PMID 39707196, 2024). "By disrupting protein synthesis in tumor cells, this approach demonstrated potential therapeutic benefits in advanced carcinomas, illustrating the crucial role eEF2 plays in cancer progression." (PMID 39707196, 2024). "In summary, eEF2 plays multiple roles in the elongation process and affects translation steps in both normal and cancer cells." (PMID 39707196, 2024). "This suggests that a promising role for eEF2 is being developed as a drug target to treat cancer, where it plays a crucial role." (PMID 39409166, 2024). "Aberrant eEF2 expression and dysregulated signaling can induce abnormal protein synthesis in cancer cells, thereby promoting cell proliferation." (PMID 39707196, 2024). "To assess the role of eEF2 in various cancer types, we also analyzed the total protein expression levels of eEF2 in several tumors using CPTAC data." (PMID 39592671, 2024). "In recent years, studies have investigated the role of diphthamide modification in eEF2 in various processes, including cancer progression and translation regulation." (PMID 39707196, 2024). "Targeting eEF2 with inhibitors presents an innovative avenue for cancer therapy; however, more research is needed to unravel the exact binding sites and regulatory mechanisms these inhibitors have on eEF2." (PMID 39707196, 2024). "This suggests that eEF2 plays a crucial role in promoting protein synthesis and sustaining rapid cancer cell proliferation in these tumors." (PMID 39592671, 2024). "In conclusion, integrating these strategies targeting eEF2’s GTPase activity, modulating PTMs, and blocking complex formation-offers a comprehensive framework for inhibiting eEF2 in cancer therapy." (PMID 39707196, 2024). "Subsequently, the phosphorylated level of eEF2 was observed to decrease in the carcinoma cells leading to reduced protein synthesis levels of SLC7A11 and GPX4, and consequently, inducing ferroptosis and autophagy." (PMID 39707196, 2024). "Supporting this, a phase 1 clinical trial (NCT01061645) explored MOC31-PE, an immunotoxin designed to target EpCAM-positive carcinomas by inhibiting protein synthesis through eEF2 modification." (PMID 39707196, 2024). "Eukaryotic translational elongation factor 2 (eEF2) is reported to be highly expressed in various cancers." (PMID 37088855, 2023). "It has been reported that translational control of the proteome, including EEF2 upregulation, is common in human cancers." (PMID 37209825, 2023). "It was observed that in breast cancer carcinoma cells, the lead PROTAC reduced total eEF2K protein levels and phosphorylation of eEF2, and importantly apoptosis was observed in this cancer model when treated with PROTAC." (PMID 36770760, 2023). "This eEF2 phosphorylation (T56) was similarly observed in TGF-β1-treated other cancer cells upon inhibition of the autophagy process by CQ treatment." (PMID 36230768, 2022). "And methylation of CDS of Snail, which recruited the YTHDF1 and eEF‐2, can trigger its translation elongation and cancer metastasis." (PMID 35678231, 2022).